C20orf96 (chromosome 20 open reading frame 96)
Synonyms: dJ1103G7.2
Tractability: PROTAC: ubiquitination databases record sites on it.
Gene: Protein-coding gene on chromosome 20 (270,863 to 290,778, reverse strand). Ensembl gene ENSG00000196476.
Subcellular location (Human Protein Atlas): Centriolar satellite
Gene Ontology:
Molecular function: protein binding
Genetic constraint (gnomAD): Loss-of-function variants: 50 observed, 48.13 expected, observed/expected ratio (o/e) 1.04, 90% interval 0.83 to 1.32. The upper end of that interval is the gene's LOEUF score, 1.32, which puts it in group 5 of 6, group 1 being the genes least tolerant of losing a copy. Missense variants: 470 observed, 430.96 expected, observed/expected ratio (o/e) 1.09, 90% interval 1.01 to 1.18. Synonymous variants: 168 observed, 151.71 expected, observed/expected ratio (o/e) 1.11, 90% interval 0.98 to 1.26.
Homologues: Orthologues: chimpanzee C20H20orf96 (97% identical), macaque C10H20orf96 (90% identical), pig C20orf96 (60% identical), dog C20orf96 (56% identical), rat C3h20orf96 (48% identical), mouse 6820408C15Rik (46% identical).